CARD9 (caspase recruitment domain family member 9)
Diseases named in the same sentence as CARD9 in open-access papers (continued):
Sharing a sentence is not in itself a finding about the gene and the disease.
Obesity (continued). "CARD9‐knockout obese mice showed enhanced autophagy by reducing p38 MAPK phosphorylation to improve obesity‐related myocardial dysfunction." (PMID 35733381, 2022). "Our data on the co‐localization of LC3B+ autophagosome with LD in CARD9 KO or Atg treatment mice suggested a potential mechanistic link between obesity‐induced inflammation and defective autophagy." (PMID 35962606, 2022). "Zinc supplementation can prevent obesity-related cardiac hypertrophy in a mouse model by inhibiting CARD9/BCL10 signaling." (PMID 35173530, 2022). "We will test that CARD9 KO interrupts this positive feedback loop and suppresses inflammation associated with HFD‐induced obesity." (PMID 35962606, 2022). "In high‐fat diet‐induced obese mice, CARD9 knockout improved obesity‐related myocardial dysfunction by reducing macrophage infiltration, inhibiting p38 MAPK phosphorylation, and enhancing autophagy." (PMID 35733381, 2022). "Recently, CARD9 was found to suppress obesity-related cardiac hypertrophy through decreasing CBM formation and p38 MAPK production." (PMID 29352133, 2018). "Here, we used MT knockout (KO) mice to explore whether MT protects against HFD-induced obesity cardiomyopathy via the CARD9/MAPKs pathway in vivo." (PMID 39897024, 2025). "As NF-κB is a downstream component of CARD9 that is in parallel with p38 MAPK, we examined whether its activation is implicated in obesity cardiomyopathy." (PMID 39897024, 2025). "CARD9 deficiency with decreased inflammation could be a protective factor in diet‐induced obesity via inhibition of the CARD9/MAPK pathway." (PMID 35432375, 2022). "Moreover, in this obesity model, CARD9 deletion reduced IL-6 and IL-1β levels in plasma as well as pro-inflammatory cytokine secretion from isolated peritoneal cells." (PMID 30867470, 2019). "The results indicated that CARD9 absence could be a vital protective factor in diet‐induced obesity via the CARD9/MAPK pathway, which may provide new insights into the development of gene knockout to improving diet‐induced obesity and metabolism disorder." (PMID 29575791, 2018). "HFD/obesity‐induced expression of both BCL10 and CARD9 further increased due to zinc deficiency." (PMID 28158919, 2017). "We hypothesize that obesity activates p38 MAPK pathway through the upregulation of Bcl10/CARD9 complex." (PMID 28158919, 2017). "Furthermore, CARD9 deletion in mice with metabolic disorders and obesity improved glucose intolerance, decreased cardiac fibrosis and cardiac dysfunction, reduced cardiac macrophage infiltration into the heart, lowered proinflammatory cytokine production, and attenuated MAPK activity 6,12,13." (PMID 39897024, 2025). "In addition to its originally proposed roles in innate immunity, available evidence suggests that CARD9 plays novel regulatory roles in the development of glucose intolerance and insulin resistance in animal models of diet-induced obesity, glucose intolerance, and insulin resistance." (PMID 40710299, 2025). "Furthermore, CARD9/BCL10 may be implicated in the synergistic effects of MT-KO and obesity on cardiac remodeling." (PMID 39897024, 2025). "Besides, obesity induced by high-fat diet is associated with an imbalance in low-density lipoprotein lipolysis in macrophages, leading to the activation of DAG-PKCδ signaling, CARD9-dependent inflammation, and impaired fat phagocytosis." (PMID 38456906, 2024). "We previously reported the regulation of CARD9 and BCL10 expression in the hearts of mice with obesity and diabetic cardiomyopathy." (PMID 39897024, 2025). "Here our in vivo data suggest that CARD9/BCL10 may activate NF-κB, but not MAPKs, to mediate obesity- or MT-induced cardiac inflammation." (PMID 39897024, 2025).
chronic mucocutaneous candidiasis (13 papers, 2011 to 2024). "Patients with CARD9 deficiency are susceptible to invasive fungal diseases and chronic mucocutaneous candidiasis (CMC) as a result of primary immune dysfunction." (PMID 29666621, 2018). "Human CARD9 deficiency (Q295X, a defective CARD9 protein with the glutamine at residue 295 substituting) was first reported in 2009 in a large consanguineous family with chronic mucocutaneous candidiasis (CMC)." (PMID 35432375, 2022). "Interestingly, two patients clinically diagnosed with HIES were shown to have previously published CARD9 mutations (p.R373P and p.Q295*) associated with chronic mucocutaneous candidiasis, respectively, deep dermatophytosis." (PMID 34390440, 2021). "Oral candidiasis, which is a component of chronic mucocutaneous candidiasis (CMC) caused by Candida albicans, is often linked with CARD9 deficiency and can serve as an indicator of the disease." (PMID 39274292, 2024). "In addition to cutaneous/subcutaneous and CNS fungal disease, many CARD9-deficient patients are also susceptible to persistent and recurrent infections of the mucosal surfaces by Candida species, collectively termed chronic mucocutaneous candidiasis (CMC)." (PMID 27092298, 2016). "Indeed, defects in several components of the Th17 pathway, ranging from the signaling molecules (CARD9, STAT1, STAT3) to the cytokines involved (IL-17), have been linked to chronic mucocutaneous candidiasis." (PMID 26308062, 2015). "In humans, deficiency in CARD9, the central signaling molecule downstream of CLRs, determines susceptibility to chronic mucocutaneous candidiasis due to a lack of Th17 response induction." (PMID 26308062, 2015). "In addition, deleterious mutations in multiple direct or downstream immune effectors, notably CLEC7A, STAT3, and CARD9, have been found in human cohorts with high prevalence of chronic mucocutaneous candidiasis (CMC) and have been recapitulated and studied in mice." (PMID 21533108, 2011).
dermatophytosis (12 papers, 2014 to 2025). A common fungal infection of the stratum corneum of the skin, hair, or nails by a dermatophyte. "Deep dermatophytosis is often associated with Caspase Recruitment Domain-containing protein 9 (CARD9) deficiency in patients." (PMID 36248888, 2022). "The susceptibility to extracutaneous deep dermatophytosis would be related to deficiencies in various immunity pathways converging in CARD9 activation and probably restricted to the myeloid cell compartment." (PMID 33343578, 2020). "Children that lack MyD88 signaling develop pyogenic infections, primarily due to Streptococcus pneumonia, and individuals with CARD9 deficiency develop mucocutaneous and disseminated candidiasis and dermatophytosis." (PMID 25621893, 2015). "Interestingly, CARD9 mutations are more common in Asia, however, African patients accounted for the majority of CARD9 mutation-related dermatophytosis cases." (PMID 38022599, 2023). "In humans, monogenic inborn errors of immunity can cause severe dermatophytosis, including autosomal recessive mutations in caspase recruitment domain family member 9 (CARD9) and autosomal dominant mutations in signal transducer and activator of transcription 1 (STAT1)." (PMID 35157719, 2022). "In addition, invasive and disseminated dermatophytosis have been associated with CARD9 (caspase recruitment domain-containing protein 9) mutations and impairment of the Th17 immune response." (PMID 34436168, 2021). "Furthermore, IL-17 impairment was also associated with inherited CARD9 deficiency and deep dermatophytosis." (PMID 33343578, 2020). "Over the last decades, cases of deep dermatophytosis have increased, particularly in immunocompromised patients, such as patients with solid organ transplantation, hematological malignancy, immunosuppressive therapy, CARD9 deficiency, and diabetes mellitus." (PMID 28164040, 2017). "CARD9 deficiency predisposes to severe dermatophytosis, mainly deep dermatophytosis." (PMID 29376922, 2015). "Recently, mutations in CARD9 were found to be the genetic cause of deep dermatophytosis." (PMID 25369198, 2014). "According to this, individuals with inherited deficiencies in CARD9, the CLR downstream adaptor molecule, are also susceptible to severe deep dermatophytosis." (PMID 33343578, 2020). "It has been described that mutation in CARD9, a key molecule in the C-type lectin receptor (CLR) signaling pathway, was associated to the development of deep dermatophytosis." (PMID 28164040, 2017).
viral infection (11 papers, 2014 to 2024). "Several PRRs are involved in the recognition of viral components, and CARD9 plays a crucial function in viral infections." (PMID 38473845, 2024). "CARD9 enhances signaling from innate immune cells to T cells, further promoting neutrophil and MΦ recruitment to sites of viral infection." (PMID 37334361, 2023). "As the classic downstream molecule of PRR signaling, CARD9 has been acknowledged to play a key role in viral infection." (PMID 36439825, 2022). "In a previous study on the role of CARD9 in proinflammatory cytokine production during viral infections, in vitro stimulation of CARD9−/− DCs with influenza A virus (IAV) also showed an impaired IL-6 and TNF-α production." (PMID 30917612, 2019). "Studies delineating the molecular pathways controlling IL-1β activation and secretion by myeloid cells in response to viral infection have identified CARD9 as a key regulator of these responses." (PMID 30127791, 2018). "Following viral infection or transfection with foreign DNA, CARD9 directly interacts with Rad50, a cytosolic DNA sensor, and these CARD9-Rad50 complexes subsequently recruit BCL10 to promote IL-1β secretion." (PMID 30127791, 2018). "Based on these, a conflicting effect of CARD9 in viral infection is unfolding before our eyes." (PMID 36439825, 2022). "CARD9 plays the positive roles in fighting fungal and viral infections through NLRP3 inflammasome." (PMID 29352133, 2018). "Beyond fungi, the Dectin-1/CARD9 pathway has been involved in bacterial and viral infections, suggesting that this mechanism could play a broader role in balancing inflammation at host-pathogen interfaces." (PMID 25771792, 2015). "CARD9 is expressed in myeloid cells, MΦs, and DCs, and CARD9 complexes with BCL10 and MALT1 contribute to innate and adaptive immune responses to viral infections." (PMID 37334361, 2023).
autoimmune disease (10 papers, 2018 to 2025). A disorder resulting from loss of function or tissue destruction of an organ or multiple organs, arising from humoral or cellular immune responses of the individual to their own tissue constituents. "As an important immune adaptor protein, CARD9 is a bridge linking the natural immune responses elicited by pathogens and acquired immune responses associated with autoimmune diseases." (PMID 36782298, 2023). "CARD9 mutations and polymorphism are common and are associated with several human diseases especially infectious diseases and autoimmune disorders including CMC and Candida meningoencephalitis." (PMID 35432375, 2022). "For example, Asian-specific haQTLs provided novel candidate variants in gene loci associated with leprosy (SIGLEC5, TNFSF15) and autoimmune disease (CARD9, IRF5, IL27, FOS) (nd 48)." (PMID 35102304, 2022). "Abnormalities of CARD9 and CARD9 signaling or CARD9 mutations or polymorphism are associated with a variety of pathological conditions including infections, inflammation, and autoimmune disorders." (PMID 35432375, 2022). "Additionally, CARD9–deficiency neutrophils are associated with some autoimmune diseases and even provide protection against a few bacteria." (PMID 33488294, 2021). "Protein kinase C delta (PRKCD) and caspase recruitment domain family member 9 (CARD9) are genes involved in B and T cell activation, and cytokine production, which are vital mechanisms underlying autoimmune disease development." (PMID 36782298, 2023). "Previous studies involving patients with other autoimmune diseases reported that CARD9 mRNA expression increased during active inflammation in patients with IBD." (PMID 36782298, 2023). "Recent studies have demonstrated potential novel roles of CARD9 in autoimmune diseases using animal models, providing interesting new insights into how this protein functions in organ-specific inflammation." (PMID 30127791, 2018).
Crohn disease (8 papers, 2014 to 2022). A gastrointestinal disorder characterized by chronic inflammation involving all layers of the intestinal wall, noncaseating granulomas affecting the intestinal wall and regional lymph nodes, and transmural fibrosis. "The CARD9 locus encodes a key pattern recognition receptor of the innate immune system, and specific variants of the CARD9 gene are involved in Crohn’s disease and ulcerative colitis pathogenesis." (PMID 29352133, 2018). "Recent studies have demonstrated that CARD9 mutations are closely associated with Crohn’s disease and ulcerative colitis development." (PMID 29352133, 2018). "CARD9 is one of the crucial receptors involved in antifungal immunity as shown in other diseases such as Crohn’s disease." (PMID 34682276, 2021). "For instance, PTVs in CARD9, RNF186 and IL23R provide protection against Crohn’s disease and/or ulcerative colitis and PTVs in ANGPTL4, PCSK9, LPA, and APOC3 protect against coronary heart disease." (PMID 29691392, 2018). "The two SNPs for Crohn’s disease are rs12720356 and rs4077515 whose host genes (TYK2 and CARD9) rank 14th and 354th by GenePANDA." (PMID 28252032, 2017).
IgA nephropathy (7 papers, 2016 to 2024). "Several loci associated with IgA nephropathy, such as CARD9 and HORMAD2, have also been associated with the risk of IBD." (PMID 39421866, 2024). "Genome-wide Association Study (GWAS) found that susceptibility genes of CARD9 and HORMAD2 for IgA nephropathy were also associated with IBD." (PMID 35850695, 2022). "ITGAM–ITGAX (rs11150612, rs11574637), VAV3 rs17019602, CARD9 rs4077515, DEFA (rs2738048, rs10086568), and HORMAD2 rs2412971 are mucosal immune defence polymorphisms, that have an impact on IgA production, described as risk loci for IgA nephropathy (IgAN)." (PMID 37685869, 2023).
atherosclerosis (6 papers, 2019 to 2024). A disease characterized by the build-up of fatty material and calcium deposition in the arterial wall resulting in partial or complete occlusion of the arterial lumen. "The acceleration of atherosclerosis is also observed in Apoe-/-Rag2-/-Card9-/- mice, ruling out a role for the adaptive immune system in the vascular phenotype of Card9 deficient mice." (PMID 37528097, 2023). "Card9 transcript was detected in myeloid cells, and macrophages in particular, including atherosclerosis-associated inflammatory and Trem2hi/Foamy macrophages." (PMID 37528097, 2023). "Previous studies suggested a role for CARD9 pathway in atherosclerosis but the underlying mechanisms remain poorly understood." (PMID 37528097, 2023). "In order to evaluate the role of adaptive immunity in the acceleration of atherosclerosis observed in Card9-deficient mice, we backcrossed Apoe-/-Rag2-/- mice with Rag2-/-Card9-/- to generate athero-prone lymphocyte (T, B, NKT)-deficient Apoe-/-Rag2-/-Card9-/- mice." (PMID 37528097, 2023). "In our study, we provided strong evidence that Card9 deficiency promoted atherosclerosis." (PMID 37528097, 2023). "Moreover, the underlying mechanisms linking Card9 engagement to atherosclerosis development remain largely unknown." (PMID 37528097, 2023). "Therefore, the pathogenic role of CARD9 in atherosclerosis may be attributed to different experimental conditions, such as types of cells used (global KO vs. hematopoietic cell KO)." (PMID 35173530, 2022). "In summary, CARD9 is a key protective pathway in atherosclerosis, modulating macrophage CD36-dependent inflammatory responses, lipid uptake and autophagy." (PMID 37528097, 2023). "Immunofluorescence staining confirmed that Card9 was expressed in atherosclerotic lesions of Apoe-/- mice at both early and advanced stages of atherosclerosis, and mainly co-localized with MOMA+ macrophages." (PMID 37528097, 2023). "Histological analysis revealed a significant decrease in atherosclerosis in the aortic sinus of rapamycin-treated Apoe-/-Card9-/-mice, compared to rapamycin-treated Apoe-/-Card9+/+mice." (PMID 37528097, 2023). "Altogether, our studies identify CARD9 as a major protective pathway in the development and complications of atherosclerosis." (PMID 37528097, 2023). "Experiments performed in Cd36-/- animals confirmed that CD36 upregulation was involved in the acceleration of atherosclerosis in Card9-/- animals." (PMID 37528097, 2023). "Here, we investigated the role of Caspase recruitment-domain containing protein 9 (Card9), a key regulator of inflammation, in atherosclerosis." (PMID 37528097, 2023). "In two recent studies, the role of CARD9 in atherosclerosis has been explored, but results reported contradictory findings." (PMID 37528097, 2023). "Global, as well as hematopoietic deletion of Card9, markedly accelerates the development of atherosclerosis, independently of the adaptive immune system." (PMID 37528097, 2023). "Caspase recruitment-domain containing protein 9 (CARD9) is a key signaling pathway in macrophages but its role in atherosclerosis is still poorly understood." (PMID 37528097, 2023). "The effect of Card9 deficiency on the upregulation of CD36 expression and lipid uptake might account for the accelerated atherosclerosis in Card9-deficient mice." (PMID 37528097, 2023).